RNU6-1335P (RNA, U6 small nuclear 1335, pseudogene)
Gene: Small nuclear RNA gene on chromosome 7 (56,340,231 to 56,340,337, reverse strand). Ensembl gene ENSG00000202296.
Homologues: Orthologues: chimpanzee U6 (99% identical), chimpanzee U6 (85% identical). Paralogues in human: RNU6-1085P (95% identical), RNU6-326P (95% identical), RNU6-20P (87% identical), RNU6-16P (86% identical), RNU6-211P (86% identical), RNU6-25P (86% identical), RNU6-35P (86% identical), RNU6-1 (85% identical), RNU6-11P (85% identical), RNU6-1316P (85% identical), RNU6-144P (85% identical), RNU6-196P (85% identical), and 1289 more.